VEGFA (vascular endothelial growth factor A)
Diseases named in the same sentence as VEGFA in open-access papers (continued):
Sharing a sentence is not in itself a finding about the gene and the disease.
tumor (continued). "Taken together, the results suggested that miR-638 might perform tumor suppressive effects in EWS, which might be mediated, at least partially, through suppressing the activity of VEGFA." (PMID 29263143, 2018). "Several STAT3 target genes are reported to be upregulated during tumour formation including B-cell lymphoma-extra large (Bcl-XL), Survivin, Hsp70, CCND1, MYC, HIF, and VEGFA, where STAT3 orchestrates the angiogenic response through HIF and VEGFA." (PMID 29301334, 2018). "In the present study, we detected elevated level of VEGFA in conditioned medium from two clones of osteotropic MDA-231 cells overexpressing IKKβ consistent of the high rate of angiogenesis and tumour cell proliferation in tumours observed in vivo." (PMID 29662632, 2018). "Likewise, the regulators of cell differentiation and proliferation, VEGFA, DLG4, CDK, NRP2 and ACHE, were also found to be down-regulated in the mtDNA-depleted tumours but presented higher levels of expression in the cells." (PMID 30208958, 2018). "Surprisingly, the average expression level of the key angiogenesis-promoting gene, VEGFA, was lowest in the 231_HM.LNm5 tumour cells, and significantly lower than in non-metastatic 231_ATCC cells." (PMID 29720474, 2018). "In attempt to dissect whether CCL3 influences the tumour milieu, we evaluated the expression of molecules involved in tumour proliferation (EGF, FGF, TGF-β and TNF-α) and angiogenesis (TGF-β1, VEGFa and VEGFb)." (PMID 28881626, 2017). "An alternative mechanism is that cancer cells may spread malignant signals to tumor microenvironment and surrounding and/or distant microenvironment, by secretion of cytokines such as TGF-β, TNF-α and VEGFA." (PMID 28881838, 2017). "Here we show that VEGFA induction of Sox2 promotes EMT and tumor metastasis." (PMID 28504716, 2017). "Whether this finding could be due to a race-related difference in the tumor’s responsiveness to bevacizumab is deserving of further study to fully evaluate if ANGPT1, ANGPT2, TEK, FGF2, MMP9 and VEGFA are promising targets for future research." (PMID 28045923, 2017). "MiR-503 inhibited tumor angiogenesis in HCC by targeting FGF2 and VEGFA." (PMID 28740507, 2017). "Many tumor cell lines constitutively express and secrete VEGFA independent of oxygen tension and the vast majority of human tumors have been shown to express VEGFA." (PMID 28415573, 2017). "Since CITED2 silencing did not affect MDA-MB-468 tumor growth or vessel formation, we also examined VEGFA expression in scramble and shCITED2-expressing MDA-MD-468 tumors." (PMID 28008154, 2017). "Furthermore, mRNA levels of VEGFA, IL8, and HBEGF were elevated in tumor-fibroblast co-cultures compared to individual cell cultures." (PMID 28977919, 2017). "Tumor development is limited without neovascularization and inhibition of VEGFA impedes tumor growth." (PMID 28415573, 2017). "Meanwhile, considering that several studies reported miR-361-5p to act its function by targeting some other factors, such as Twist1, VEGFA and FOXM1, it remains to be explored whether other targets may contribute to the anti-tumor effect of miR-361-5p." (PMID 29132384, 2017). "VEGFA induced DNMT3A, but not related DNMT3B or DNMT1, and DNMT3A knockdown prevented VEGFA‐mediated miR‐128 loss and the increases in Bmi1 expression and OVCA tumor sphere formation in vitro." (PMID 28179359, 2017). "Finally, we evaluated the cell viability after down-regulation of VEGFA by small interfering RNAs and the reaction to bevacizumab in MMQ tumor stem-like cells." (PMID 28163656, 2017). "PFKFB4 and VEGFA, on the other hand, were not evaluated in tumor specimens because of the variability and unpredictability of their expression in response to hypoxia in the three NB cell lines examined." (PMID 29117193, 2017).
tumor (continued). "Additionally, the vascular endothelial growth factor A (VEGF-A) and its receptor VEGFR-1/2 were interacted to affect to tube formation of tumor cells by TGF-β1, at same time, EGF/EGFR also has similar activity." (PMID 27613831, 2016). "In contrast, VEGFA was a uniquely inhibited UPR in CPA-treated LLC tumors, suggesting that CPA/6d inhibits VEGFA-dependent angiogenesis in this tumor model." (PMID 27515027, 2016). "A tumor suppressor miRNA, miR-34a-5p, targeted several critical cancer genes, including CDK6, CCND1, CCNE2, E2F3 in the cell cycle pathway and VEGFA in the angiogenesis pathway." (PMID 27329603, 2016). "Compared to the neovascularization effect of VEGFA, myelomonocytic cell depletion by clodronate liposomes had a greater impact on tumor growth (data not shown)." (PMID 27391260, 2016). "The expression of miR-847 is decreased in gastric cancer, which activates the signal transducer and activator of transcription 3 (STAT3)/vascular endothelial growth factor A (VEGF-A) pathway, increases tumor angiogenesis, and promotes the development and progression of gastric cancer." (PMID 27464701, 2016). "Still, the VEGFR2 and c-Src activities were suppressed in the late stage of tumour growth in WT mice, showing a restriction in VEGFA signalling independent of VEPTP." (PMID 27005951, 2016). "Elevated levels of vascular endothelial growth factor A induce excess centrosomes in endothelial cells, but how other features of the tumor environment affect centrosome over-duplication is not known." (PMID 27977771, 2016). "In-situ prebiomarkers such as VEGFA, VEGF-R2 or CA9, as well as circulating prebiomarkers such as VEGFA, VEGFR1, ICAM1, IL6, IL8 or circulating tumor cells count were reported to predict bevacizumab benefit, but this predictive value was generally weak and rarely confirmed." (PMID 26921265, 2016). "Moreover, FABP4 was found to be induced by VEGFA and/or the NOTCH pathway in endothelial cells, and inhibition of FABP4 blocks most of the VEGFA effects, suggesting its role in tumour angiogenesis." (PMID 26959740, 2016). "Importantly, systemic delivery of anti-VEGFA/CCL2 or pre-miR-1, pre-miR-206 and anti-miR-31 significantly inhibited tumor angiogenesis, TAMs accumulation, tumor growth and lung metastasis." (PMID 27541266, 2016). "Although our model supports findings of increased VEGFA expression in response to hypoxia, this loop was not sufficient to induce Bcl-2-mediated tumor cell survival in the in vivo setting." (PMID 26959744, 2016). "Besides, the expression of VEGFA, another potential target gene of miR-497, was significantly higher in HCC tissues than that in matched adjacent non-tumor tissues." (PMID 26336827, 2015). "This explains why NCOA1 could enhance the transcriptional activity of the VEGFa promoter under both hypoxia and normoxia conditions and also implies a role of NCOA1 in upregulating VEGFa expression and tumor angiogenesis under both conditions." (PMID 26287601, 2015). "Interestingly, the levels of SRC and PPARB/D expression were highly and significantly correlated in these tumours, as were the expression levels of PPARB/D andTGFB1 and MMP19, respectively, and to a lesser extent, MMP2, VEGFA, VIM and SNAI1." (PMID 24203162, 2014). "We found that the vascular endothelial growth factor A (VEGFA), a member of the PDGF/VEGF growth factor family that promotes angiogenesis through nitric oxide synthase, was significantly up-regulated in UCB in cancer tissue compared to non-tumor tissue." (PMID 24622401, 2014). "Therefore, the inhibitory effect of TGF-beta on VEGFA expression and angiogenesis provides another important and novel mechanistic basis for TGF-beta tumor and metastasis suppressor function." (PMID 23536895, 2013). "According to the well-documented role of MMP-7, IL-8, and VEGFA for cancer development and tumor growth, synergistic effects between HH/EGF mediated signaling pathways may accelerate tumor initiation and support tumor growth." (PMID 23762360, 2013).
tumor (continued). "Macrophages isolated from HCC tumor tissue expressed significantly higher levels of VEGFA and PDGFB mRNA compared to those detected in non-tumor-infiltrating macrophages (approximate 2.07-fold upregulated, P = 0.015 and approximate 2.33-fold upregulated, P = 0.011, respectively, n = 7)." (PMID 24194900, 2013). "We further examined VEGFA expression and microvessel density (MVD) in the tumor samples." (PMID 24194905, 2013). "The angiogenic factors VEGFA and FGF2 directly promote tumor angiogenesis." (PMID 22895562, 2012). "The pro-angiogenic factors, such as VEGFA, bFGF, and MCP-1, etc., are involved in the activation, mobilization and recruitment of EPCs from the bone marrow, and the differentiation of EPCs into ECs in some ischemic diseases and during tumor growth." (PMID 21152281, 2010). "Vascular endothelial growth factor-A121 expression was also significantly increased in tumours displaying N2 status as compared to those without nodal involvement (N0)." (PMID 16495931, 2006). "Serum and plasma vascular endothelial growth factor-A were not significantly elevated in the vein draining the tumours, despite tumour cell expression of vascular endothelial growth factor-A." (PMID 12454774, 2002). "Mechanistically, this subset responds to hypoxia by expressing VEGFA to directly promote tumor angiogenesis while highly expressing the chemokines CXCL2, CXCL3, and CXCL8 to establish a chronic inflammatory microenvironment that indirectly fosters tumor progression and vascularization." (PMID 41514936, 2026). "Accordingly, adding VEGFA inhibitors or multi-kinase inhibitors such as Sunitinib simultaneously with HIF inhibitor in clinical trials may well suppress angiogenesis of glioblastoma, slow tumor progression, and achieve improved OS." (PMID 41575610, 2026). "Nowadays, most of the research focuses on targeting key regulatory nodes such as VEGFA and exploring its joint application with armored CAR-T, immune checkpoint blocking, and metabolic regulatory drugs, aiming at reconstructing the perfusion and immune cell infiltration capacity of tumor areas." (PMID 41226585, 2025). "Consequently, TEM depletion might lead to vascular deterioration, ANG2 neutralization could enhance the response to vascular VEGFA blockage, and TEM recruitment inhibition could decrease tumor development." (PMID 40422244, 2025). "CSCs themselves modify the tumor microenvironment to replicate the conditions of stem cell niches, promote epithelial-mesenchymal transition (EMT) in nearby tumor cells, and alter the microenvironment of distant tissues by secreting factors such as VEGFA, LOX, TGFβ, and TNFα to promote metastasis." (PMID 40813991, 2025). "Ligand-receptor inference identifies VEGFA–VEGFR2 and CXCL12–CXCR4 pairs as the strongest directional interactions in this niche, while exhausted PD-1+ CD8+ cells accumulate at its stromal boundary, expressing CCR5 and ITGAE yet failing to cross into the tumour core." (PMID 40740859, 2025). "UBE2CP3 has been shown to promote hepatocyte VEGFA secretion into the tumor microenvironment and enhance tumor cell-induced angiogenesis through activation of the ERK/p70S6K/HIF-1α pathway, while ERK signaling has previously been noted to play a role in the regulation of tumor EMT." (PMID 40028033, 2025). "VEGFA can recruit suppressive immune cells such as TAMs, Tregs, and MDSCs, although it may also increase vascular permeability, thus improving drug delivery of SRA737 + LDHU to tumours in vivo." (PMID 40507298, 2025). "Given that RT has been shown to enhance the expression of VEGFA, TGF‐β1, and EMT‐related genes in vitro, we sought to determine whether Y332D could counteract RT‐induced upregulation of VEGFA and TGF‐β1, as well as the promotion of EMT in 4T1 tumor tissues via Immunohistochemistry (IHC) staining." (PMID 40470716, 2025).
tumor (continued). "Recently, an alternative strategy inhibiting tumour neoangiogenesis using bevacizumab, a humanised monoclonal antibody raised against vascular endothelial growth factor A (VEGF-A), showed no significant improvement on patient survival, indicating the need for improved therapeutics." (PMID 38803685, 2024). "Functional enrichment analysis showed that pathways such as angiogenesis (VEGFA-VEGFR2) and complement cascade were significantly downregulated in the NATs, while alternative splicing and cell cycle pathways were suppressed in the tumor tissues after Col003 treatment." (PMID 39430252, 2024). "For example, blocking IL1B expression in IL1B+ macrophages could prevent the production of angiogenesis-promoting MC4 via the IL1B/ADRB2 pathway, resulting in the inhibition of tumor growth, a reduction in the TNF+/VEGFA+ ratio, and an increase in patient prognosis." (PMID 39840068, 2024). "Additionally, a xenograft tumor model was established to further validate these findings in vivo, demonstrating that circSNX6 plays a crucial role in HCC progression by interacting with miR-383-5p and VEGFA." (PMID 38589413, 2024). "miR-20b-5p could modulate vascular endothelial growth factor A (VEGFA) transcription by targeting hypoxia-inducible 4 factor 1-alpha (HIF1α), may act as a tumor suppressor by hindering MMP-2 expression, leading to cell cycle arrest, and also has a regulatory function in oxygen balance." (PMID 39188680, 2024). "Our analysis results could also explain the lack of response to bevacizumab, a VEGFA inhibitor, since other types of vascular growth factors are highly expressed in the MM tumor microenvironment, leading to possible compensation and drug resistance." (PMID 39596117, 2024). "Moreover, we found that the tumor tissue of muscone-treated mice expressed lower amounts of the proangiogenic factors VEGFA and PDGFB than did control mice, which potentially explained the rise in pericyte and BM coverage within tumor vessels of muscone-treated mice." (PMID 38898449, 2024). "As cRCC is a highly vascular tumor, over the past years, the treatment of RCC has been focused on the inhibition of VEGFA/KDR signaling pathway with an increasing number of new drugs, including tyrosine kinase inhibitors as well as anti-VEGFA humanized monoclonal antibody." (PMID 39000466, 2024). "Cancer is characterized by up-regulation of pro-angiogenic factors such as VEGFA, FGF, PDGF and angiopoietin and down-regulation of anti-angiogenic factors such as thrombospondin, vasopressor and endothelial inhibitor, leading to neovessel formation and tumor progression." (PMID 39193386, 2024). "Cross-talk between the EREG and VEGFA ligands in the tumor microenvironment has also been found in a single cell transcriptome analysis uncovering that EREG mediates cuproptosis in glioma cells, where high cuproptosis activation scores were significantly enriched in VEGFA + malignant cells." (PMID 38398101, 2024). "However, inhibiting VEGFA could negate its suppression of HGF-dependent MET phosphorylation and tumor cell migration and lead to a more invasive phenotype." (PMID 37214395, 2023). "Importantly, it has been recognized that VEGFA also plays a crucial role in tumor immunosuppression, and our results suggest that USP22 may participate in tumor immune escape via modulation of VEGFA expression." (PMID 36906615, 2023). "However, other gene sets, such as TGF-β signaling, tumor angiogenesis and VEGFA targets, are not significantly different between the two groups." (PMID 37404825, 2023). "Immunofluorescent detection of tissue samples with high and low CuAS showed that VEGFA and CD99 were also highly expressed in tissues with high CuAS, and the results were opposite in tissues with low CuAS, which provided a new idea for us to intervene in cuproptosis-related tumor cells." (PMID 36647156, 2023).
tumor (continued). "In conclusion, we showed that C-VGB3, which reproduces a binding region of VEGFB, could interfere with the interaction between VEGFA and VEGFR2 and inhibit angiogenesis and tumor growth via suppression of PI3K/AKT/mTOR and PLCγ/ERK1/2 pathways in both endothelial and tumor cells." (PMID 37375853, 2023). "Aberrant expression of VM production-related proteins (MMP2, MMP9, VEGFA, Laminin, Wnt3a, RHOA) as well as immune checkpoint (PD-L1) in tumors and the occurrence of EMT process are considered to be important drivers of VM formation and tumor development as well as metastasis." (PMID 37407689, 2023). "Indeed, ccRCC is a highly angiogenic malignancy due to the fact that the tumor cells overproduce hypoxia inducible VEGFA mRNAs in the absence of VHL, irrespective of oxygen availability." (PMID 36831657, 2023). "No or low expression of VEGFA was found in nine tumour tissues and 57 peritumoral tissues." (PMID 36729917, 2023). "Since innate immune cells can contribute to tumor suppression boosting a strong adaptive immune response, we hypothesized that infiltration on M1 macrophages in the TME by BRAF/VEGFA targeting would enhance the efficacy of the ICB, which primarily unleashes anticancer T‐cell response." (PMID 37183363, 2023). "Direct comparison between KIRC tumor tissues and morphologically unchanged (control) kidney samples revealed a lack of statistical difference between the expression of SHH and approximately 1.25- and 1.5 higher immunoreactivity of GLI1 and VEGFA proteins, respectively, in cancer cells." (PMID 37964226, 2023). "In addition, other metastasis related genes (VEGFA, MMP-2 and MMP-9) decreased in tumor cells." (PMID 37853415, 2023). "Therefore, results of the current study enhances the available understanding on tumor angiogenesis and shows that STK24/STAT3/VEGFA signaling pathway may be a novel therapeutic target for treatment of patients with NSCLC." (PMID 36720310, 2023). "Nrf2 activity in transformed cells lowers ROS and inhibits tumor growth in vivo by mechanisms such as apoptosis sensitization and a reduced angiogenic/hypoxic response via HIF-1(hypoxia-inducible factor-1) instability and VEGFA (vascular endothelial growth factor A) suppression." (PMID 36747120, 2023). "Furthermore, mCAFs were enriched in angiogenesis-related pathways that send multiple angiogenesis-related signals to blood ECs, including PGF, VEGFA, and PDGF, indicating that mCAFs are the key CAFs in promoting tumor angiogenesis and inducing tumor growth and metastasis in HPSCC in vivo." (PMID 37853464, 2023). "Anti‐tumour effects were assessed by measuring pathologic complete response (pCR), survival analysis, immunohistochemistry for E‐cadherin, VEGF, MMP9, MMP2 and Ki‐67, serum measurement of IFNγ and IL‐4, and gene expression analysis of CD105, VEGFa, VEGFR2 and COX2." (PMID 37581480, 2023). "We also observed that MDSC-secreted VEGFA and multiple chemokines CCL2, CXCL1, CXCL2, CXCL3, and CXCL8 could act on endothelial cells via VEGFA-KDR/FLT1 and CCL2/CXCLs-ACKR1 interactions, which were crucial for tumor angiogenesis." (PMID 37475874, 2023). "VEGFA, the most potent angiogenic-stimulant member of the VEGF superfamily, which can be produced by a variety of cell types, including endothelial cells, platelets, macrophages, and tumor cells, has gained significant attention for its crucial role in dynamic homeostasis and pathological processes." (PMID 38089766, 2023).